MKRN3 (makorin ring finger protein 3)
Diseases named in the same sentence as MKRN3 in open-access papers (continued):
Sharing a sentence is not in itself a finding about the gene and the disease.
Obesity (2 papers, 2024 to 2025). Accumulation of substantial excess body fat. "In addition, epigenetic changes, such as polymorphisms in the MKRN3 and LIN28B genes, as well as prenatal and postnatal environmental factors, intestinal microbiota, and endocrine disruptors, are also associated with the adolescent development of children and adolescents with obesity." (PMID 40150457, 2025). "Kanber and colleagues described a patient with deletions in MKRN3, MAGEL2, and NDN, exhibiting only obesity, developmental delay, and a high pain threshold as the primary clinical criteria for PWS." (PMID 38737552, 2024).
premature ovarian failure (2 papers, 2015 to 2020). "Of course, the link between the MKRN3 mutation and premature ovarian failure has to be confirmed studying large cohorts of adult mutated patients." (PMID 26499472, 2015).
Temple syndrome (2 papers, 2019 to 2023). "Similar to MKRN3, DLK1 gene also locates in a maternal imprinting region located in 14q32, which is originally reported as a critical region of Temple syndrome." (PMID 31687022, 2019).
breast tumors (1 paper, 2018). "Using data available from The Cancer Genome Atlas (TCGA), we correlated expression of four genes (MKRN3, TPPA, ZNF280B, and XKR6) with DNA methylation in 553 breast tumors." (PMID 30352973, 2018).
congenital hypogonadotropic hypogonadism (1 paper, 2022). Congenital hypogonadotropic hypogonadism (CHH) is a rare disorder of sexual maturation characterized by gonadotropin (Gn) deficiency with low sex steroid levels associated with low levels of follicle stimulating hormone (FSH) and luteinizing hormone (LH). "MKRN3 has also been found to interact with OTUDS, a deubiquitinase protein linked to congenital hypogonadotropic hypogonadism that can act by counteracting the effects of MKRN3 during puberty." (PMID 36187104, 2022).
Esotropia (1 paper, 2015). A form of strabismus with one or both eyes turned inward ('crossed') to a relatively severe degree, usually defined as 10 diopters or more. "Among the other three reported patients carrying MKRN3 loss of function mutations, one had clinodactily and hyperlordosis whereas the remaining two patients had esotropia." (PMID 26499472, 2015).
glioma (1 paper, 2023). A benign or malignant brain and spinal cord tumor that arises from glial cells (astrocytes, oligodendrocytes, ependymal cells). "In this study, the tumor-suppressor function of MKRN3 in glioma was discovered depending on E3 ubiquitin ligase activity." (PMID 37723588, 2023).
hypothalamic hamartoma (1 paper, 2023). "CPP may incorporate genetic alterations, such as MKRN3, DLK1, and KISS1; mutations in the epigenetic factors that regulate the HPG axis, such as Lin28b and Let 7; syndromes; central lesions such as hypothalamic hamartoma; and others." (PMID 38021712, 2023). "CPP may occur as genetic alterations, such as MKRN3, DLK1, or KISS1;as a part of mutations in the epigenetic factors that regulate the HPG axis, such as Lin28b and let-7; or as a part of syndromes, central lesions such as hypothalamic hamartoma, and others." (PMID 38021712, 2023).
lymph node metastasis (1 paper, 2021). "Univariate Cox regression analyses revealed that age, sex, clinical stage, lymph node metastasis, T classification, and status of MKRN3 expression were significantly associated with overall survival (all P < 0.05)." (PMID 34689784, 2021). "Additionally, the forest plot analysis of overall survival showed statistically significant associations between age, clinical stage, lymph node metastasis, T classification metastasis, and MKRN3 expression and the outcome of SCCHN patients (all P < 0.05)." (PMID 34689784, 2021).
lymphoma (1 paper, 2016). A malignant (clonal) proliferation of B- lymphocytes or T- lymphocytes which involves the lymph nodes, bone marrow and/or extranodal sites. "However it is interesting to note that Peg12 and Mkrn3 are much more strikingly down-regulated in the Lymphoma data set than in the NSCs as they are normally only very lowly expressed in the lymphoma cell lines." (PMID 26981392, 2016). "Genes uncovered in the Lymphoma analysis are consistent with previous reports in a different system that profiled male embryos, where the expression of imprinted genes such as Peg12 and Mkrn3 was shown to be disturbed in the absence of Smchd1." (PMID 26981392, 2016).
maple syrup urine disease (1 paper, 2018). An autosomal recessive inherited disorder caused by mutations in the BCKDHA, BCKDHB, DBT, and DLD genes. "ddPCR and iPCR analysis showed that the transgene consisted of five fragments of the BAC clone containing the Mkrn3 gene region, and that the transgene was inserted into Bckdhb, homozygous deletion of which causes the maple syrup urine disease phenotype." (PMID 29703985, 2018).
Schaaf-Yang syndrome (1 paper, 2025). "This cluster comprises the MKRN3, NDN, MAGEL2, and SNHG14 genes, the loss of function of which contributes to Prader-Willi and Schaaf-Yang syndromes." (PMID 40877933, 2025).
tumor (11 papers, 2019 to 2024). "the tumor suppressive function of MKRN3 is dependent on its E3 ubiquitin ligase activity, and MKRN3 missense mutations were found to impair MKRN3-mediated PABPC1 ubiquitination in patients." (PMID 36531055, 2022). "Reconstitution of MKRN3 in NSCLC cells directly abrogates tumor growth in vitro and in vivo, suggesting MKRN3 functions as a tumor suppressor in NSCLCs." (PMID 35281811, 2022). "The density and intensity of MKRN3 expression in SCCHN tumor tissues were significantly increased compared to those of para-carcinoma tissues." (PMID 34689784, 2021). "In this study, we found that elevated MKRN3 expression was correlated with the aggressive tumor characteristics in SCCHN patients, making MKRN3 an independent prognostic predictor for the survival of SCCHN patients." (PMID 34689784, 2021). "Our data provide evidence that MKRN3 plays an important role in tumor progression and may serve as a critical promoter of SCCHN." (PMID 34689784, 2021). "The functional enrichment clustering of MKRN3 showed that a total of 63 categories from GO biological process, such as DNA synthesis and repair, cellular response to tumor microenvironment, regulation of cellular cycle, and translation were identified as important for cancer development." (PMID 34689784, 2021). "Six patients underwent molecular testing on tumor DNA: two carried marked IC2-LoM, two exhibited loss of heterozygosity (LOH) at chromosome 11p15, one carried somatic pathogenic variants of CTNNB1 and GNAS genes, and one carried somatic pathogenic variants of the MKRN3 and CYP17A1 genes." (PMID 39682154, 2024).
cancer (6 papers, 2019 to 2024). A tumor composed of atypical neoplastic, often pleomorphic cells that invade other tissues. "Using gene ontology and Kyoto Encyclopedia of Genes and Genomes analyses, we determined that MKRN3 may be involved in the regulation of synthesis and metabolism and cell growth, death and motility, as well as cancer pathways associated with SCCHN progression." (PMID 34689784, 2021). "These factors were closely related to the occurrence and development of cancer, suggesting that MKRN3 expression exhibits a strong relationship with the progress of SCCHN." (PMID 34689784, 2021). "KEGG analysis based on these nodes revealed that 17 pathways in cancer, RNA synthesis and metabolism, and cell growth, death, and motility that were significantly enhanced during SCCHN progression were regulated by MKRN3." (PMID 34689784, 2021). "However, the roles of NCBP2, MKRN3, and MRPL47 in cancers are still unclear." (PMID 33505420, 2020).
infection (1 paper, 2011). The state of being infected such as from the introduction of a foreign agent such as serum, vaccine, antigenic substance or organism. "A second strong hit was MKRN3 (markorin 3, ring finger protein, 3) where 2 individual siRNAs rescued infection (4.7 fold)." (PMID 22082156, 2011).
MKRN3 also shares sentences with these, for which no sentence is quoted: central precocious puberty 2 (2 papers); metabolic disorders (2); Cognitive impairment (1); Down syndrome (1); hypothalamic tumors (1); Infertility (1); lung carcinoma (1); melanoma (1); neurological disorders (1); premature menopause (1); systemic lupus erythematosus (1).